ATM (ATM serine/threonine kinase)
Diseases named in the same sentence as ATM in open-access papers (continued):
Sharing a sentence is not in itself a finding about the gene and the disease.
tumor (continued). "It is possible that the inherited genetic variants in ATM may affect the capacity of DSB repair in a way that would associate with the patterns of specific large-scale genomic alterations and rearrangements in a subset of cells in the tumor due to yet unknown genetic or microenvironment modifiers." (PMID 25010664, 2014). "The central role of ATM in the prevention of genomic instability, as well as the occurrence of the activation of the DDR at early stages of tumor initiation, prompted several groups to investigate the role of ATM expression in several tumor models in vivo." (PMID 24681585, 2014). "It has been reported that ATM can act as a tumor suppressor in liver cancer, by directly phosphorylating Tax1 binding protein 2 (TAX1BP2), a cyclin-dependent kinase 2-regulated tumor suppressor." (PMID 25247188, 2014). "We analyzed the protein expression of MRE11, MDC1, ATM, ATR and BRCA1 by immunohistochemistry (IHC) in 97 SOC samples, and correlated with clinical parameters including age, tumor grades, clinical stage, status of menstruation and chemotherapy." (PMID 24752797, 2014). "Moreover, they could show that Atm deficiency lowered tumor angiogenesis and enhanced the antiangiogenic action of agents that block VEGF, suggesting that ATM activation in response to ROS may positively impinge on tumor growth because of its ability to promote angiogenesis." (PMID 24681585, 2014). "ATM +/XRCC1 +, DNA-PK +/XRCC1 + and ATR +/XRCC1 + tumours had the worst survival compared to ATM-/XRCC1-, DNA-PK-/XRCC1- and ATR-/XRCC1- tumours in our study." (PMID 26674120, 2014). "ATM and RBL2 are already known as negative regulators of cell cycle which support their role as tumor suppressor genes." (PMID 22485171, 2012). "As first recognised by Halazonetis, Bartek and colleagues, tumour cells often display an activated DDR as evidenced by foci of DDR signaling proteins such as 53BP1 and activated ATM." (PMID 22240795, 2012). "They found that patients whose tumours had normal expression of BRCA1 or ATM had significantly longer survival, with ATM being an independent prognostic marker." (PMID 23154512, 2012). "This is consistent with the observations that inactivation of ATM diminishes MYC-induced apoptosis and augments MYC-driven tumor development." (PMID 20111719, 2010). "Caffeine as well as more specific inhibitors of ATM (KU55933) or ATM and ATR (CGK733) have recently been shown to induce cell death in drug-induced senescent tumor cells." (PMID 19903334, 2009). "ATM and ATR/Chk1 signalling pathways were manipulated using siRNA-mediated depletions or specific inhibitors in two tumour cell lines or fibroblasts derived from patients with inherited mutations." (PMID 19119425, 2009). "While the selectivities of ATM inhibition and CHK1 inhibition for FA defective tumor are low individually, the effect of combining them is synergistic, yielding an effect that is likely pertinent clinically." (PMID 19371427, 2009). "ATM responds to DNA DSBs by phosphorylating protein kinases such as CHK1, initiating cascading reactions of downstream effector molecules, thus providing tumor cells with sufficient time for DDR." (PMID 41473689, 2025).
tumor (continued). "In our previous work, we demonstrated that ATM knockdown or inhibition did not affect tumor growth in nude mice." (PMID 40825766, 2025). "CHK1/2, serving as key downstream effector molecules of the ATR and ATM signaling pathways, primarily trigger cell cycle arrest by precisely regulating G1/S and G2/M checkpoints, thereby exerting core regulatory functions in the DDR network of tumor cells." (PMID 41473689, 2025). "We identified newly emerging mutations in genes that were not covered by our targeted NGS panel such as ATM, NOTCH2, EP300, ARID1A and MAP3K1 and also noticed an increase in tumor mutational burden (TMB) in some cases during progression." (PMID 40973765, 2025). "Additionally, pharmacological blockade of ATM/Chk2 and ATR/Chk1 axes enhances the effects of immunotherapy by increasing tumor immunogenicity, promoting T-cell infiltration and activating immune responses." (PMID 40422251, 2025). "Telomere attrition can elicit a persistent DNA damage response, thereby activating the ATM/ATR-checkpoint kinase 1 (CHK1) pathway and facilitating immune surveillance evasion by upregulating PD-L1 expression, ultimately promoting tumor cell immune tolerance and progression." (PMID 40510156, 2025). "In the JAVELIN tumour-agnostic study, which evaluated the combination of anti-PD-L1 avelumab and PARPi talazoparib in patients with BRCA1/2 or ATM pathogenic alterations, ORR was 26.4%, thereby not meeting the prespecified target ORR of 40%." (PMID 41188872, 2025). "The clinical management of patients with ATM-related neoplasms is not clearly defined by international guidelines, as also the risk management in unaffected family members harboring the variant." (PMID 39984762, 2025). "Besides PARP-BRCA1/2 pairs, DDR sensor kinases ATM, ATR and DNA-PK recently gained attention as synthetic lethal partners in different tumour types, as demonstrated by the increasing number of their inhibitors in clinical trials." (PMID 40091075, 2025). "By impairing chemokine-induced DLBCL cell motility, ATM-3507 could limit the ability of DLBCL cells to migrate into tissues and establish extranodal sites of tumor growth." (PMID 41268543, 2025). "Moreover, the Tpm3.1/3.2 inhibitor ATM-3507 (Anisina) inhibits the in vitro survival, growth, and motility of the B16-F1, C8161, WM164, S462, CMTRL-100, and ST88–14 tumor cell lines, and reduces the growth of human melanoma xenografts in immunodeficient mice." (PMID 41268543, 2025). "ATM is a known gene active in radiation-induced DNA damage repair, but LIG4 and RNF8 are less well known genes in radiation response in HNSCC, although their role in DNA repair has been well studied in other tumor models." (PMID 40768535, 2025). "As in the targeted monotherapies, also in the combinatorial setting, routine multi-gene NGS of both tissue and circulating tumor DNA is now the standard of care, with the 2025 NCCN guideline mandating HRR-gene screening (BRCA1/2, ATM, PALB2, etc.)for every mCRPC patient." (PMID 40806607, 2025). "Tumor sequencing revealed LOH in CHEK2 and ATM, as well as CCND1 and GAB2 amplifications." (PMID 38091153, 2024). "ATM mediates the downregulation of SLC7A11 after radiotherapy, resulting in ferroptosis; this anti-neoplastic effect of radiotherapy is enhanced by the combination of immune checkpoint inhibitors, e.g., anti-PD-L1 or anti-CTLA4 antibodies, in tumor models." (PMID 38778030, 2024). "The autophagy findings were closely reflected in our data examining tumor cell killing, where the dose-dependent killing effect was profoundly reduced with knock down of Beclin1 or ATG5 but remained present in cells that had ATM or AMPKα knocked down." (PMID 38329728, 2024).
tumor (continued). "We also found that putative tumor suppressors, such as FOXP1, STK4, and ATM were frequently hypermethylated and silenced whereas oncogenes, such as UHRF1, MPZL1, CDK14, RACGAP1, and RAB13, were hypomethylated and overexpressed suggesting that DNA methylation changes contribute to PTCL development." (PMID 38464090, 2024). "CtDNA-detected BRCA and ATM genes exhibited an 81% positive percentage agreement and 92% negative percent agreement with tumor tissue biopsy." (PMID 38927984, 2024). "M4076, an ATP-competitive ATM inhibitor with an IC50 value <1 nM, inhibits tumor cell growth by blocking DSB repair and enhances the sensitivity of tumor cells to radiation therapy both in vitro and in vivo.1258,1259 A phase I clinical trial of M4076 in advanced solid tumors is active (NCT04882917)." (PMID 38763973, 2024). "Similarly, enriched LOH events covered tumour suppressor genes such as APC (5q22.2), ATM (11q22.3), and CDX2 (13q12.2)." (PMID 39461959, 2024). "The effect may be attributed to the deletion of ATM protein, leading to higher TMB, and tumor cells with high TMB expression may have more neoantigens and therefore be more sensitive to immunotherapy." (PMID 37305685, 2023). "If tumour genetic testing was performed, the panellists considered further germline testing appropriate in patients with high-volume mHSPC (CHAARTED criteria) having a BRCA1/2 tumour (L)PV or a non-BRCA1/2 tumour (L)PV (eg, ATM, CHEK2)." (PMID 36874601, 2023). "This requires more investigative work comparing these various radiation modalities in combination with inhibitors such as those targeting PARP, ATM, ATR, DNA-PKcs and CHK1, to confidently determine a specific strategy that is efficacious in radiosensitising specific tumours." (PMID 37695845, 2023). "Similarly, alterations in DNA damage response genes such as ATM, CDK12, and those of the RAD family (RAD51C, RAD54L) were observed across multiple tumour types." (PMID 37120671, 2023). "To identify previously unknown tumor‐suppressive pathways involved in the DDR, we interrogated a catalog of BCL driver genes and a dataset of ATM and ATR substrates." (PMID 37485814, 2023). "In addition, the co-inhibition of WEE1 and ATM inhibited the activation of the FAK-Src-CREB signaling pathway, which is closely related to the migratory invasive ability of tumor cells." (PMID 37305685, 2023). "This difference might be an advantage for targeting WEE1 instead of ATM and CHK2 to block G2/M arrest in terms of tumor specificity and limited normal tissue toxicity issues." (PMID 36313934, 2023). "The results of this study, by demonstrating clear divergences in the impact of dysregulation of ATM, ATR, and CHK2 on important tumor characteristics, shed new insight into how early decisions to turn off cell cycle regulation can direct the course of ensuing disease." (PMID 37390209, 2023). "This DDR molecular pathway, via its key ATM and ATR proteins, could promote tumor angiogenesis under hypoxic conditions." (PMID 37371032, 2023). "Therefore, many clinical trials have investigated HR repair as a potential target for tumor therapy, including ATR, ATM, and Rad51." (PMID 37684630, 2023). "Costs for patients treated with olaparib, enzalutamide, or abiraterone increased substantially in the subgroup of patients with a tumor harboring at least one of three prespecified gene alterations (BRCA1, BRCA2, or ATM) versus those with at least one of 15 prespecified gene alterations." (PMID 37829336, 2023). "One patient had ATM and CHEK2 mutations identified in ctDNA drawn 7 months after tumor molecular testing without these alterations." (PMID 36933202, 2023).
tumor (continued). "Given that the knockout of STAG2 sensitized tumor cells to ATMi and PARPi, we hypothesized that ATM inhibition may synergize in vitro and in vivo with PARP inhibition to promote tumor cell killing." (PMID 37985839, 2023). "The top-scoring genes altered in the four gene sets included many genes associated with cell apoptosis and DNA damage, such as GADD45A, DDIT3, BAX, CASP1, CASP8, ATM, and FANCD2, demonstrating that diminishment of RAD51 contributes to the tumor suppressive effect." (PMID 37175611, 2023). "Nevertheless, under hypoxic conditions, this DDR molecular pathway, via its key ATM and ATR proteins, could promote tumor angiogenesis." (PMID 37371032, 2023). "In numerous phase II and III clinical studies, little or no response to multiple PARPi was reported in diverse tumor types carrying HR mutations in genes such as CHEK2, ATM, FANCA, and CDK12." (PMID 37761329, 2023). "Specifically, higher mB7-H3 was present in tumours with bi-allelic BRCA2 mutation mutations (n=13, p=0.003) or ATM protein loss (n=16, p=0.02) than in those without DDR." (PMID 36114082, 2023). "Somatic alterations in pre-specified genes (ATM, RB1, FANCC and ERCC2) or increased tumor mutational burden did not improve the positive predictive value of cCR." (PMID 37783966, 2023). "All objective responses in this trial were in tumours harbouring BRCA2, ATM or CHEK2 alterations." (PMID 37365284, 2023). "BRCA1, BRCA2, ATM, PALB2, and BAP1 were the DNA damage response GA found in our tumor samples." (PMID 36831055, 2023). "A protective DNA damage reaction increases apoptosis through E2F1-Foxo because it stabilizes E2F1 through ATM and Chk2 phosphorylation, whereas the Foxo-dependent arm of E2F1 signaling in charge of apoptosis was found to be reduced in most tumor types examined relative to counterpart normal samples." (PMID 37754262, 2023). "In this study, mutations in the genes ARID1A, APC, ERBB4, NCOR1, PDGFRA, ATM, and CDKN2A were either non-recurrent or of very low frequency, while none of the 14 sequenced EP tumours harboured mutations in the genes HRAS, EGFR, or RB1." (PMID 34045664, 2022). "Radiotherapy-activated ATM and IFNγ from immunotherapy-activated CD8+ T cells would synergistically enhance ferroptosis and tumor lipid oxidation, indicating the correlation between ferroptosis agonists and chemoradiotherapy via immunotherapy for the first time." (PMID 36439512, 2022). "Similarly, it was identified in the ATM/HER2 protein level with tumour grade (p < 0.001), disease stage (p = 0.008), tumour shape (p < 0.001), in addition to lymph node (p = 0.046) and metastasis (p = 0.001)." (PMID 36056635, 2022). "In the PROfound study, 81% of cfDNA samples yielded an NGS result, and with tumor tissue as a reference, the positive and negative percentage agreement for BRCA and ataxia-telangiectasia mutated (ATM) mutations was 81% and 92%, respectively." (PMID 36551924, 2022). "Another key mechanism by which ATM and ATR inhibitors selectively enhance tumor cell inactivation when combined with IR) may be through the inducing of senescence." (PMID 36338767, 2022). "While PTEN-deficient tumor cells were not dependent on DNA-PK for IR resistance nor activated ATR during IR, they showed a significant dependence for the DNA damage kinase ATM." (PMID 35477555, 2022). "Furthermore, we confirmed three genes (ATM, NBN and MCPH1) to be downregulated in clinical CRPC tumor samples in our in vitro models." (PMID 36139600, 2022).
tumor (continued). "Moreover, blockages of ATM, MAPK, and mTOR signaling with respective inhibitors prevented citrate‐induced upregulation of ACLY in tumor cells." (PMID 34747157, 2022). "ATM, SIRPA, and LILRB2 are potential targets in tumor immunotherapy." (PMID 33868359, 2021). "ATR, ATM and DNA-PK inhibition may also increase MHC-I expression in tumor cells to effect antigen presentation and T cell infiltration." (PMID 34298632, 2021). "Therefore, the effect of ATM and CK2 inhibition was evaluated on ex vivo tumor slice cultures derived from two VHL− and VHL+ ccRCC PDX models, respectively." (PMID 33540838, 2021). "By immunohistochemical staining of Sirt3, p-ATM, p-Chk2 and γ-H2AX in each group of tumor tissues, it was also found that the activation of γ-H2AX was more pronounced in Sirt3 knockdown group, and the radiation-induced activation of p-ATM was significantly attenuated." (PMID 34405009, 2021). "Since ATM is required both to kill EBVaGC and induce EBV lytic reactivation in our study, we questioned whether ATM is required to suppress tumor development by chemotherapy." (PMID 34503060, 2021). "Whilst the role of PALB2 and ATM is fairly well established in PC, RAD50 is not among the genes generally associated with this tumour." (PMID 34034685, 2021). "The patients (KMUH cohort) with two good prognostic factors, such as ATM–high expression and small tumor size or negative lymph node, showed superior OS to other subgroups." (PMID 34068585, 2021). "Phenformin can activate ATM and repair double‐stranded DNA damage, which is not conducive to inhibiting the growth of tumor cells." (PMID 33742560, 2021). "BRCA1 methylated tumours are also sensitive to PARP inhibition, as are tumours with mutations in other genes that function in repair of double strand breaks (DSBs), including RAD51C, RAD51D, ATM and PALB2, where tumours are described as having a “BRCAness” phenotype." (PMID 34445211, 2021). "Consistent with previous findings, the ATM deletion did not accelerate tumor progression (solid red line)." (PMID 34445646, 2021). "Moreover, the ATM/ATR inhibitor VE-822 sensitized xenograft tumors to etoposide treatment, and analysis of tumor sections showed that VE-822 decreased the frequency of centrosome clustering." (PMID 33397932, 2021). "In this scenario, co-upregulation of MAPK14 (together with ATF2) might enable the competitive edge for MAPK14- as compared to ATM-mediated ATF2 activation, thereby driving tumor progression and drug resistance." (PMID 33803354, 2021). "Therefore, the dual inhibition of ATM and its key downstream factors allowed BKM120 to completely reverse the HCQ-improved HR repair efficiency in the tumor cells." (PMID 34844627, 2021). "ATM and ATR signaling is deeply involved in multiple processes in tumor biology." (PMID 34483751, 2021). "Besides DDR, ATM and ATR involve in cellular homeostasis, immune regulation, senescence, tumorigenesis and tumor progression." (PMID 34483751, 2021). "ATM has been reported to influence the cell cycle through regulation of PLK1, and PLK1 is the G2/M checkpoint that alleviates cell cycle arrest in the G2/M phase in various tumour cells." (PMID 34565365, 2021). "Multivariate analysis indicated that the combination of high ATM and low Ki67 is prognostic for improved OS, independent of tumor size, grade, and lymph node status (p = 0.02)." (PMID 33224881, 2020). "Moreover, the ATM inhibitor (AZD0156) suppressed another two repair pathways, resulting in BTC tumor suppression due to synthetic lethality." (PMID 33182492, 2020). "Average p-values across Calu6, Calu3, H358 and RH2 tumours show enrichment for genes residing in the EGF, NF-κβ, TGF-β, mTOR/PI3K/AKT, integrin, ATM and G1/S checkpoint signalling pathways that was generally greater in tumours exposed to dry powder than aqueous 5AZA." (PMID 32103148, 2020).